HIVEP3 (HIVEP zinc finger 3)
Description:
Plays a role of transcription factor; binds to recognition signal sequences (Rss heptamer) for somatic recombination of immunoglobulin and T-cell receptor gene segments; Also binds to the kappa-B motif of gene such as S100A4, involved in cell progression and differentiation. Kappa-B motif is a gene regulatory element found in promoters and enhancers of genes involved in immunity, inflammation, and growth and that responds to viral antigens, mitogens, and cytokines. Involvement of HIVEP3 in cell growth is strengthened by the fact that its down-regulation promotes cell cycle progression with ultimate formation of multinucleated giant cells. Strongly inhibits TNF-induced NF-kappa-B activation; Interferes with nuclear factor NF-kappa-B by several mechanisms: as transcription factor, by competing for Kappa-B motif and by repressing transcription in the nucleus; through a non transcriptional process, by inhibiting nuclear translocation of RELA by association with TRAF2, an adapter molecule in the tumor necrosis factor signaling, which blocks the formation of IKK complex. Interaction with TRAF proteins inhibits both NF-Kappa-B-mediated and c-Jun N-terminal kinase/JNK-mediated responses that include apoptosis and pro-inflammatory cytokine gene expression. Positively regulates the expression of IL2 in T-cell. Essential regulator of adult bone formation.
Synonyms: KBP-1; KBP1; KIAA1555; KRC; ZAS3; SHN3; FLJ16752; Schnurri-3; ZNF40C
Tractability: PROTAC: ubiquitination databases record sites on it.
Gene: Protein-coding gene on chromosome 1 (41,506,365 to 42,035,925, reverse strand). Ensembl gene ENSG00000127124.
Subcellular location: Cytoplasm; Nucleus
Subcellular location (Human Protein Atlas): Nucleoplasm
Pathways (Reactome):
Gene expression (Transcription): Regulation of RUNX2 expression and activity
Gene Ontology:
Molecular function: protein binding; DNA-binding transcription factor activity, RNA polymerase II-specific; RNA polymerase II cis-regulatory region sequence-specific DNA binding; DNA binding
Biological process: positive regulation of DNA-templated transcription; regulation of transcription by RNA polymerase II; regulation of DNA-templated transcription
Cellular component: nucleus; cytoplasm
Genetic constraint (gnomAD): Loss-of-function variants: 52 observed, 157 expected, observed/expected ratio (o/e) 0.33, 90% interval 0.26 to 0.42. The upper end of that interval is the gene's LOEUF score, 0.42, which puts it in group 1 of 6, group 1 being the genes least tolerant of losing a copy. Missense variants: 2,761 observed, 3,137.3 expected, observed/expected ratio (o/e) 0.88, 90% interval 0.85 to 0.91. Synonymous variants: 1,258 observed, 1,305.7 expected, observed/expected ratio (o/e) 0.96, 90% interval 0.92 to 1.01.
Homologues: Orthologues: chimpanzee HIVEP3 (99% identical), macaque HIVEP3 (93% identical), dog HIVEP3 (88% identical), guinea pig HIVEP3 (86% identical), rabbit HIVEP3 (83% identical), rat Hivep3 (80% identical), mouse Hivep3 (80% identical), tropical clawed frog hivep3 (48% identical), zebrafish hivep3b (33% identical), zebrafish hivep3a (27% identical). Paralogues in human: HIVEP2 (31% identical), HIVEP1 (27% identical), ZNF831 (12% identical), RREB1 (10% identical), SALL3 (8% identical), SALL1 (8% identical), SALL4 (7% identical), BCL11B (6% identical), BCL11A (6% identical), ZNF536 (6% identical), ZNF516 (6% identical), SALL2 (5% identical), and 2 more.
Diseases named in the same sentence as HIVEP3 in open-access papers:
HIVEP3 is named in the same sentence as 38 diseases in open-access papers, as found by Europe PMC text mining. Sharing a sentence is not in itself a finding about the gene and the disease. The quoted sentences say what the papers report.
inflammatory bowel disease (2 papers, 2017 to 2024). A spectrum of small and large bowel inflammatory diseases of unknown etiology. "From the DMR analysis, TRIM40 has recently been associated with inflammation in the context of inflammatory bowel disease, RNF14 regulates mitochondrial and immune-related functioning, and HIVEP3 regulates the development of innate-like T cells." (PMID 38296944, 2024).
Parkinson’s (2 papers, 2017 to 2025). "Meanwhile, Cluster 25 exhibited relatively lower RBS-R scores than those of the other clusters but higher DCDQ and SCQ scores, with HIVEP3 and NUBPL being associated with Parkinson’s disease." (PMID 40440618, 2025).
retinal disease (2 papers, 2019 to 2020). "HIVEP3 has been reported to be expressed ubiquitously, including the human retina, but it has not been implicated to retinal disease in any species." (PMID 32150541, 2020).
Allergy (1 paper, 2021). An allergy is an immune response or reaction to substances that are usually not harmful. "Comparing the direction of methylation to the independent allergy data set, four genes exhibited the opposite direction of patterning (HIVEP3, TRAT1, BCL7A and SLC442A), while the DNA methylation patterning of the remaining genes were identical between the groups." (PMID 34193262, 2021).
leukemia (1 paper, 2022). A malignant (clonal) hematologic disorder, involving hematopoietic stem cells and characterized by the presence of primitive or atypical myeloid or lymphoid cells in the bone marrow and the blood. "HIVEP3 expression discrepancy needs to be confirmed considering that the normal marrows should contain mainly mature cells, while leukemia marrows are full of immature cells." (PMID 35535739, 2022). "HIVEP3 expression was examined by qRT‐PCR in leukemia cell lines treated with ferroptosis compounds in vitro." (PMID 35535739, 2022). "Furthernore, altered HIVEP3 expression at the mRNA or protein level was confirmed in sorted leukemia cells and blast cells in bone marrow tissues." (PMID 35535739, 2022).
prostate carcinoma (1 paper, 2021). A carcinoma that arises from epithelial cells of the prostate gland. "In prostate cancer, the HIVEP3 gene functions as an oncogene." (PMID 34946969, 2021).
cancer (6 papers, 2017 to 2025). A tumor composed of atypical neoplastic, often pleomorphic cells that invade other tissues. "Hypomethylation at this site may lead to increased HIVEP3 expression, potentially enhancing NF-κB pathway activity, which is frequently dysregulated in cancer." (PMID 40791616, 2025). "Stenotrophomonas, an opportunistic pathogen with increased colonization/infection in cancer patients, exhibited extensive positive associations with the hypermethylation of genes, including multiple TSGs in CRC, such as ESR1, RASSF5, DIRAS1, CADM1, ST5, GJB2, FAM172A, and HIVEP3." (PMID 38840170, 2024).
tumor (6 papers, 2021 to 2025). "HIVEP3, a transcription factor, binds to genes involve in cell progression and differentiation, while LZTS1 acts as a tumor suppressor." (PMID 40463504, 2025). "We infer that HIVEP3, by collaborating with the ribosomal protein (RP) family, such as RPL15, RPL34, and RPS24, could regulate tumor cell cycle and apoptosis and promote tumor proliferation and infiltration metastasis, angiogenesis, or other malignant biological behaviors." (PMID 35535739, 2022). "Furthermore, HIVEP3 that functions as transcription factor is related to modulation of immunoglobulin gene rearrangement, cell survival and TNF-signaling as well as osteoblastic bone and tumor formation." (PMID 34348642, 2021).
infection (2 papers, 2021 to 2024). The state of being infected such as from the introduction of a foreign agent such as serum, vaccine, antigenic substance or organism. "The current study expanded on these two studies by identifying 18 SNPs associated with MAP tissue infection through re-sequencing and fine-mapping in both Holstein and Jersey breeds when the region between EDN2 and HIVEP3 was evaluated." (PMID 34026885, 2021).
HIVEP3 also shares sentences with these, for which no sentence is quoted: osteoporosis (7 papers); Osteopenia (2); rheumatoid arthritis (2); acute myeloid leukemia (1); astrocytoma (1); atherosclerosis (1); brain tumors (1); breast carcinoma (1); cognitive disorder (1); colon carcinoma (1); endometriosis (1); glioma (1); hematological malignancies (1); lung adenocarcinoma (1); lung carcinoma (1); male infertility (1); melanoma (1); metabolic disorders (1); Obesity (1); osteopetrosis (1); osteosclerosis (1); Paget disease (1); peripheral nerve injury (1); peripheral neuropathy (1); postmenopausal osteoporosis (1); renal carcinoma (1); retinal degeneration (1); retinal disorder (1); thyroid (1).